RNA5SP530 (RNA, 5S ribosomal pseudogene 530)
Gene: Ribosomal RNA gene on chromosome 9 (41,237,440 to 41,237,557, reverse strand). Ensembl gene ENSG00000277049.
Homologues: Orthologues: chimpanzee 5S_rRNA (97% identical), chimpanzee 5S_rRNA (96% identical), chimpanzee 5S_rRNA (95% identical), macaque 5S_rRNA (82% identical), guinea pig 5S_rRNA (64% identical). Paralogues in human: 5S_rRNA (92% identical), RNA5SP528 (92% identical), RNA5SP532 (92% identical), RNA5S1 (75% identical), RNA5S10 (75% identical), RNA5S11 (75% identical), RNA5S12 (75% identical), RNA5S13 (75% identical), RNA5S14 (75% identical), RNA5S15 (75% identical), RNA5S16 (75% identical), RNA5S17 (75% identical), and 26 more.